WWOX (WW domain containing oxidoreductase)
Diseases named in the same sentence as WWOX in open-access papers (continued):
Sharing a sentence is not in itself a finding about the gene and the disease.
ovarian carcinoma (continued). "The results demonstrated that following transfection of the WWOX gene, ovarian cancer stem cells expressed significantly higher levels of Wnt-5α, JNK and caspase-3 mRNA, indicating activation of the Wnt/JNK/caspase-3 signaling pathway." (PMID 25891642, 2015). "The results demonstrated that the WWOX gene can be stably expressed in ovarian cancer stem cells and inhibits the proliferation of ovarian cancer stem cells." (PMID 25891642, 2015). "The results demonstrated that following transfection of the WWOX gene, ovarian cancer stem cells expressed significantly lower levels of cyclin E, CDK2, cyclin D1 and CDK4 proteins than the empty plasmid group and the control group." (PMID 25891642, 2015). "Further studies are required to elucidate what the specific target of the WWOX gene is and its role in regulating cell cycle and apoptosis of ovarian cancer stem cells." (PMID 25891642, 2015). "Our previous study identified that the WW domain-containing oxidoreductase (WWOX) gene significantly affects the biological behavior of human ovarian cancer cells." (PMID 24959289, 2014). "In the current study, to further investigate the impact of the WWOX gene on ovarian cancer stem cells, the eukaryotic expression vector, pcDNA3.1-WWOX, was transfected into ovarian cancer stem cells to investigate the impact on EMT and its mechanism of action." (PMID 24959289, 2014). "In order to further investigate the impact of WWOX genes on ovarian cancer stem cells, the current study selected human ovarian cancer stem cells and the human epithelial ovarian carcinoma cell line, HO-8910 as experimental models." (PMID 24959289, 2014). "An EMT exists in ovarian cancer stem cells, and the WWOX gene inhibits the cellular proliferation of ovarian cancer stem cells and reduces their invasive capability." (PMID 24959289, 2014). "The present study aimed to further explore the correlation between the abnormal methylation of the WWOX gene and epithelial ovarian cancer." (PMID 24137423, 2013). "The aim of this study was to explore the effects of 5-Aza-2′-deoxycytidine (5-Aza-CdR), a DNA methylation inhibitor, on the methylation state and function of the WWOX gene in the HO-8910 ovarian cancer cell line." (PMID 24137423, 2013). "The present study revealed that the WWOX gene was in a state of hypermethylation in the HO-8910 ovarian cancer cell line." (PMID 24137423, 2013). "In the present study, the in vivo and in vitro experiments revealed that aberrant methylation of the WWOX gene was the main reason for the reduction in gene transcription and expression, which may be closely associated with the occurrence and development of ovarian cancer." (PMID 24137423, 2013). "Immunoblotting analysis from normal ovarian samples demonstrated consistently strong WWOX expression while 37% ovarian carcinomas showed reduced or undetectable WWOX protein expression levels." (PMID 15982416, 2005). "Immunoblotting analysis demonstrated that full length WWOX protein was the predominant WWOX isoform expressed in both normal ovary and ovarian carcinomas." (PMID 15982416, 2005). "We correlated WWOX protein expression with ovarian carcinoma histotypes and clinico-pathological parameters." (PMID 15982416, 2005). "We performed WWOX protein expression analyses by means of immunobloting and immunohistochemistry on normal ovaries and specific human ovarian carcinoma Tissue Microarrays (n = 444)." (PMID 15982416, 2005). "The goal of these studies was to evaluate WWOX protein expression levels in ovarian carcinomas to determine if they correlated with clinico-pathological parameters, thus providing additional support for WWOX functioning as a tumor suppressor." (PMID 15982416, 2005). "We provide evidence that WWOX protein expression is frequently altered and highly variable in ovarian carcinomas." (PMID 15982416, 2005).
ovarian carcinoma (continued). "Furthermore, in ovarian cancer, WWOX influences the cell cycle of ovarian cancer stem cells and inhibits their proliferation by downregulating the expression levels of cyclins, specifically cyclin E-CDK2 and cyclin D1-CDK4." (PMID 41228229, 2025). "Furthermore, WWOX expression promotes apoptosis in ovarian cancer cells cultured in suspension in vitro." (PMID 41228229, 2025). "Notably, WWOX expression significantly enhances paclitaxel-mediated cell death in epithelial ovarian cancer (EOC) cells." (PMID 41228229, 2025). "In addition, our previous studies have demonstrated that WWOX alters the biological phenotype of ovarian cancer stem cells, and is important in the formation and progression of ovarian cancer." (PMID 25789010, 2015). "The present study demonstrated that the WWOX gene may be an important molecular target for the treatment of ovarian cancer in the future." (PMID 25891642, 2015). "The results demonstrated that following transfection of the WWOX gene, the cell cycle of ovarian cancer stem cells was arrested in the G0/G1 phase, indicating that the WWOX gene significantly inhibits the cell cycle of ovarian cancer stem cells." (PMID 25891642, 2015). "The results indicated that ovarian cancer stem cells possessed high tumorigenicity, however, WWOX expression led to a lowered tumorigenesis rate and a longer time for tumors to form, suggesting that WWOX expression reduces tumorigenicity in these cells." (PMID 25789010, 2015). "In conclusion, these results indicated that the WWOX gene reverses the EMT phenomenon in ovarian cancer stem cells by regulating the expression of various transcription factors and reduces tumor invasion, providing a potential novel therapeutic target for ovarian cancer." (PMID 24959289, 2014). "The WWOX gene was in a state of methylation in the HO-8910 ovarian cancer cell line." (PMID 24137423, 2013). "In this study we analyzed WWOX protein expression pattern in normal ovary and ovarian carcinomas." (PMID 15982416, 2005). "In this ovarian cancer study, we also observed that Serous and Endometroid histotypes express normal or high WWOX but two rare but well described ovarian carcinoma histotypes, mucinous and clear cell, demonstrated a higher frequency of loss of WWOX protein expression." (PMID 15982416, 2005). "Since our original cloning of WWOX abundant evidence has accumulated indicating that this gene likely plays a role in either tumor initiation or progression in various neoplasias including ovarian cancer." (PMID 15982416, 2005). "The present study provides an experimental basis for ovarian cancer gene therapy, as the WWOX gene was found to exhibit a significant effect on the biological behavior of ovarian cancer stem cells and thus, may present a novel therapeutic target for ovarian cancer treatment." (PMID 25789010, 2015). "One study demonstrated that normal ovarian tissue expressed high levels of the WWOX protein, however, the expression was reduced or absent in ovarian cancer patients; furthermore, a loss of WWOX expression was detected in 70% of ovarian mucinous adenocarcinoma and 42% of clear cell carcinoma." (PMID 25891642, 2015). "Furthermore, the WWOX gene may promote apoptosis of ovarian cancer stem cells by upregulating the expression levels of Wnt-5α, JNK and caspase-3." (PMID 25891642, 2015). "However, when WWOX was expressed, these cells exhibited significantly decreased resistance to these drugs, indicating that WWOX may reverse the drug resistance of ovarian cancer stem cells." (PMID 25789010, 2015). "In the sphere-forming assay, WWOX-expressing cells exhibited a significantly diminished sphere-forming ability compared with the control cells (empty vector-transfected cells or untransfected cells), indicating that WWOX expression inhibits the self-renewal capability of ovarian cancer stem cells." (PMID 25789010, 2015).
ovarian carcinoma (continued). "Therefore, the WWOX gene may reverse the EMT in ovarian cancer stem cells by regulating the expression of the EMT regulatory factors, Elf5 and Snail." (PMID 24959289, 2014). "The WW domain-containing oxidoreductase (WWOX) gene has been shown to down-regulate the expression of cyclin E-CDK2 and cyclin D1-CDK4, affecting the cell cycle of ovarian cancer stem cells." (PMID 41154849, 2025). "We examine the ER stress-mediated apoptotic response to paclitaxel in WWOX-transfected epithelial ovarian cancer (EOC) cells and following siRNA knockdown of WWOX." (PMID 28749468, 2017). "The WWOX gene can downregulate the expression levels of cell cycle proteins cyclin E-CDK2 and cyclin D1-CDK4, which affects the cell cycle of ovarian cancer stem cells." (PMID 25891642, 2015). "Our method is able to identify the known cancer drivers and further nominate candidates that exhibit higher breakpoint proximity than expected by random chance, such as DMD and LRRN3 in esophageal cancer, NF1 in ovarian cancer, CDK12 in uterine cancer, and WWOX in colorectal cancer." (PMID 36163358, 2022). "In the present study, the experimental results suggest that the WWOX gene may downregulate the protein expression levels of cyclin E-CDK2 and cyclin D1-CDK4 to affect cell proliferation and the cell cycle of ovarian cancer stem cells." (PMID 25891642, 2015). "By contrast, the WWOX gene may upregulate the expression levels of Wnt-5α, JNK and caspase-3 to promote apoptosis of ovarian cancer stem cells." (PMID 25891642, 2015). "Furthermore, the WWOX gene can upregulate the mRNA expression levels of Wnt-5α, JNK and caspase-3, thus contributing to apoptosis of ovarian cancer stem cells." (PMID 25891642, 2015). "Our analysis by immunoblotting and IHC demonstrated that about one third of ovarian carcinomas displayed extremely reduced or absent WWOX protein expression." (PMID 15982416, 2005). "The specificity of this WWOX antibody in the immunoblotting analyses was demonstrated by observing no immunoreactive products in cell extracts from the PEO1 ovarian carcinoma cell line used as negative control." (PMID 15982416, 2005). "Specifically PR negative ovarian carcinomas also lacked WWOX expression." (PMID 15982416, 2005).
bladder cancer (18 papers, 2013 to 2025). "Studies on bladder cancers revealed a critical role of WWOX in the tumorigenesis and loss of its protein expression correlates with higher tumor grade, more advanced stage, and shorter progression-free survival or overall survival." (PMID 35841413, 2022). "A significant reduction or loss of expression of WWOX has been observed mainly in breast cancer, but also in liver and bladder cancers." (PMID 36364214, 2022). "Of these, WWOX is situated in direct proximity to the chromosomal locus 16q24 whose allelic loss is implicated in the tumor progression of 20% to 45% of bladder cancers (BLCAs)." (PMID 33718178, 2021). "Studies on bladder cancer patients indicate a relationship between progressive loss of WWOX protein expression and higher tumor grade, more advanced stage, larger tumor size and shorter progression-free survival." (PMID 33691672, 2021). "Chromosomal breakage at this site is more common in bladder cancer patients who are tobacco smokers which suggests the importance of WWOX gene loss regarding bladder carcinogenesis." (PMID 33718178, 2021). "We propose that the WWOX gene should be considered as a tumor suppressor in bladder cancer, particularly based on our careful analysis of variants demonstrating overexpression of two genes (W/A or W/C)." (PMID 33718178, 2021). "CSE has been shown to cause hypermethylation and inactivation of the WW domain-containing oxidoreductase (WWOX) gene in T-24 human bladder cancer cells." (PMID 28587272, 2017). "The −508 to −174 bp region of the WWOX gene promoter was methylated in 31% of bladder cancer samples and was also associated with reduced levels of WWOX gene mRNA, which is consistent with results observed in glioblastoma multiforme specimens." (PMID 25295115, 2014). "At present, FHIT and WWOX promoter methylation associated with the loss of gene expression has been reported for various types of cancers, including lung, breast, esophageal and bladder cancer." (PMID 24137446, 2013). "Our previous studies have shown that WWOX strongly activates both the inflammatory response and ROS generation in the AY-27 bladder cancer cell line." (PMID 40006511, 2025). "This study explored the beneficial effects of overexpressing WW domain-containing oxidoreductase (WWOX) in AY-27 cells encapsulated in an injectable gelatin hydrogel for potential therapeutic applications in bladder cancer." (PMID 40006511, 2025). "As for cell viability, our previous research on bladder cancer also demonstrated that WWOX decreases mitochondrial redox potential, with the explanation for this possibly to be found in the link between TNF and reactive oxygen species." (PMID 36979157, 2023). "In the present study, we demonstrated that expression of WWOX in bladder cancer AY-27 cells suppresses proliferation." (PMID 36364214, 2022). "The modulation of WWOX in bladder cancer cells has a dramatic effect on cell morphology and proliferation." (PMID 36364214, 2022). "The aim of this study was to investigate the role of WWOX in the regulation of ROS and cell senescence, which is intriguing in terms of the possible mechanism of WWOX contributing to bladder cancer." (PMID 36364214, 2022). "The cytogenic locus of the WWOX gene overlaps with the second most active fragile site, FRA16D, which is present at a higher frequency in bladder cancer (BLCA) patients with smoking habit, a known risk factor of this tumor." (PMID 34204827, 2021). "Downregulation of WWOX in bladder cancer cell line intensified ability of single cell to grow into colony, mitochondrial redox potential and proliferation rate." (PMID 33691672, 2021). "The WWOX tumor suppressor gene, located in a common fragile site, is involved in the regulation of carcinogenesis in many tissue types including bladder cancer." (PMID 33691672, 2021).
bladder cancer (continued). "As the WWOX interacts with many proteins including transcription factors AP-2 α and γ, the present study examined relationship between these proteins in bladder cancer hence we also pursued this issue in further bioinformatics analyzes." (PMID 33691672, 2021). "Through global in silico profiling we determined that WWOX alters disease-free survival of bladder cancer patients and modulates vital processes through AP-2 downstream effectors." (PMID 33691672, 2021). "Our research indicates that WWOX possesses tumor suppressor properties in bladder cancer but consecutive examination is required to entirely understand the contribution of AP-2γ or AP-2α." (PMID 33691672, 2021). "One of the mechanisms regulating WWOX expression in bladder cancer is methylation of both the promoter region and the first exon of the gene." (PMID 33691672, 2021). "Examination of bladder cancer samples in the present study revealed that LOH occurred at a higher frequency in intron 1 (marker D16S518) than in intron 8 (marker D16S3096) of the WWOX gene: 64.5 vs. 25.8%, respectively." (PMID 25295115, 2014). "Our study suggests that WWOX, an ROS-dependent senescence-induced gene, could be further studied for its therapeutic implications in bladder cancer." (PMID 36364214, 2022). "WWOX functions as a tumor-suppressor gene in a number of cancers, including both breast and bladder cancer, but the underlying functional mechanisms of WWOX have not been fully explained." (PMID 36364214, 2022). "Moreover, WWOX-induced senescence is closely dependent on intercellular ROS accumulation, supporting the induction of cellular senescence in bladder cancer cells after WWOX overexpression." (PMID 36364214, 2022). "Therefore, the aim of the current study was to determine the role of the WWOX in modulating cellular pathways activated by AP-2α and AP-2γ transcription factors in bladder cancer." (PMID 35563688, 2022). "In addition, we found that WWOX strongly activates the inflammatory response and ROS generation in the AY-27 bladder cancer cell line." (PMID 36364214, 2022). "Presumably, the interaction between WWOX and both transcription factors regulates thousands of genes, hence the aim of the present study was to determine WWOX, AP-2α, and AP-2γ function in modulating biological processes of bladder cancer." (PMID 33718178, 2021). "Therefore, the aim of the present study was to investigate the functionality of WWOX, AP-2α and AP-2γ in G3 and G4 bladder cancer and identify changes in biological processes between bladder cancer grades." (PMID 34204827, 2021). "Until now, only one publication reported that WWOX may regulate cell cycle and apoptosis but also reduces tumorigenicity in mice; research was done on 5637 bladder cancer cell line (grade 2)." (PMID 33691672, 2021). "Reduced expression of the WWOX gene has been reported and associated with poor prognosis and unfavorable outcome in different kinds of cancers such as breast, ovarian, non-small cell lung (NSCLC), and bladder cancer." (PMID 25612104, 2015). "The results of the present study indicate that, in bladder cancer, WWOX gene expression levels may be reduced by two mechanisms: LOH or promoter region methylation." (PMID 25295115, 2014). "However, a large number of tumor samples is required to demonstrate the influence of WWOX gene alternations on the clinical status of bladder cancer." (PMID 25295115, 2014). "Given that the implication of WWOX/AP-2 in ncRNA networks merits further investigation, this study aimed at constructing RNA interactomes containing WWOX and AP-2α/γ and then investigating the most relevant observation using data from bladder cancer cell lines and patients affected by this disease." (PMID 37519886, 2023).
bladder cancer (continued). "Therefore, the primary aim of this study was to determine the role of the WWOX gene in biological cancer-related processes in the aggressive bladder cancer cell line CAL-29 (derived from grade 4 tumor) and identify its connections with the AP-2 family of transcription factors." (PMID 33691672, 2021). "As LOH influence appears to be less important in the regulation of WWOX expression in bladder cancer, it is possible that epigenetic mechanisms are more relevant; this is supported by the fact that smoking may increase hypermethylation of regions corresponding to WWOX exon 1 or its promoter." (PMID 33718178, 2021). "WWOX and TFAP2A demonstrate tumor suppressor synergism in high-grade bladder cancer, similar to intermediate grade." (PMID 37859819, 2023). "WW Domain Containing Oxidoreductase (WWOX) belongs to the unusual tumor suppressors, whose molecular function is not fully understood in bladder cancer, especially regarding interaction with Activator Protein 2 (AP-2) α/γ transcription factors." (PMID 33691672, 2021). "Thus, previous phenotypic observations that supposedly WWOX is an EMT inhibitor, AP-2γ an EMT enhancer while AP-2α an MET inducer, were found to be explainable at the molecular level in bladder cancer." (PMID 35563688, 2022). "In addition, our previous research proved a frequent (47.5%) loss of heterozygosity (LOH) located in intron 1 (microsatellite marker D16S518) of the WWOX gene, together with positive correlation between the levels of WWOX and CCND1 mRNA in bladder cancer patients." (PMID 33691672, 2021).